EMILIN3 (elastin microfibril interfacer 3)
Synonyms: C20orf130; EMILIN5; dJ620E11.4
Tractability: Antibody: UniProt places it where antibodies can reach, with medium confidence; UniProt predicts a signal peptide or a membrane-spanning region; its Gene Ontology location is reachable by antibodies, with medium confidence.
Gene: Protein-coding gene on chromosome 20 (41,359,962 to 41,366,818, reverse strand). Ensembl gene ENSG00000183798.
Subcellular location: Secreted, extracellular space, extracellular matrix
Subcellular location (Human Protein Atlas): Golgi apparatus; Predicted to be secreted
Pathways (Reactome):
Extracellular matrix organization: Molecules associated with elastic fibres
Gene Ontology:
Molecular function: identical protein binding; protein binding; extracellular matrix constituent conferring elasticity
Cellular component: extracellular matrix; EMILIN complex; cytoplasm
Genetic constraint (gnomAD): Loss-of-function variants: 45 observed, 51.18 expected, observed/expected ratio (o/e) 0.88, 90% interval 0.69 to 1.13. The upper end of that interval is the gene's LOEUF score, 1.13, which puts it in group 4 of 6, group 1 being the genes least tolerant of losing a copy. Missense variants: 924 observed, 973.16 expected, observed/expected ratio (o/e) 0.95, 90% interval 0.9 to 1. Synonymous variants: 430 observed, 426.62 expected, observed/expected ratio (o/e) 1.01, 90% interval 0.93 to 1.09.
Homologues: Orthologues: chimpanzee EMILIN3 (99% identical), macaque EMILIN3 (96% identical), pig EMILIN3 (87% identical), rabbit EMILIN3 (87% identical), mouse Emilin3 (84% identical), guinea pig EMILIN3 (83% identical), dog EMILIN3 (77% identical), rat Emilin3 (75% identical), tropical clawed frog emilin3 (37% identical), zebrafish emilin3a (20% identical). Paralogues in human: EMILIN2 (23% identical), EMILIN1 (22% identical), MMRN2 (14% identical), MMRN1 (12% identical).
Diseases named in the same sentence as EMILIN3 in open-access papers:
EMILIN3 is named in the same sentence as 15 diseases in open-access papers, as found by Europe PMC text mining. Sharing a sentence is not in itself a finding about the gene and the disease. The quoted sentences say what the papers report.
glioma (5 papers, 2016 to 2025). A benign or malignant brain and spinal cord tumor that arises from glial cells (astrocytes, oligodendrocytes, ependymal cells). "EMILIN3 (Elastin-like polypeptide 3) is primarily studied for its interactions with the tumor microenvironment and its effects on glioma cell behavior." (PMID 40535771, 2025). "The results from TCGA dataset and Beroukhim dataset indicated that EMILIN3 was significantly up-regulated in Brain and CNS Cancers than in normal tissues." (PMID 32175193, 2020). "In contrast with normal tissues, Beroukhim dataset and Bredel research was founded that significantly lower expressions of EMILIN3 in Brain and CNS Cancers." (PMID 32175193, 2020). "The EMILIN3 gene augments the aggressiveness of low-grade gliomas, a prevalent type of brain tumor." (PMID 40918512, 2025). "In comparison to other glioma subtypes, the GS2 exhibited higher expression levels of IBSP, PLA2G2A, NNMT, CA9, and MMP9, while the GS5 showed higher expression levels of CHI3L1, IGFBP2, EMILIN3, MEOX2, and PDPN." (PMID 38332637, 2024). "Two of these genes (EMILIN-3 and CDH4) have never been reported in the context of glioma research so far." (PMID 27782828, 2016).
anaplastic astrocytoma (1 paper, 2020). "This study found a distinct EMILIN3 expression pattern in anaplastic astrocytoma; EMILIN3 was also used to identify LGG tumor grades." (PMID 32175193, 2020). "Additionally, there were higher expression levels of EMILIN3 and MMRN1 in anaplastic astrocytoma compared to normal brain tissue." (PMID 32175193, 2020).
COVID-19 (1 paper, 2025). A disease caused by infection with severe acute respiratory syndrome coronavirus 2. "Of note, the expression of EMILIN3 was highly upregulated in both the COVID-19 and MDD datasets." (PMID 40918512, 2025). "EMILIN3, OPA3, and TFCP2 are likely to be potential shared hub genes in both COVID-19 and depression." (PMID 40918512, 2025). "We used LASSO and RF methods to identify EMILIN3, OPA3, and TFCP2, as potential hub genes for both COVID-19 and MDD." (PMID 40918512, 2025). "Furthermore, when comparing COVID-19- and MDD-related hub genes, we found that three genes, i.e., TFCP2, OPA3, and EMILIN3, overlapped." (PMID 40918512, 2025).
dentin caries (1 paper, 2020). "In contrast, dentin caries induced a significant increase in the signal intensity for EMILIN-3, which was particularly strong in odontoblast processes within tertiary dentin." (PMID 32948785, 2020).
depression (1 paper, 2025). "Furthermore, in the GSE101521 dataset, OPA3 and TFCP2 genes, but not EMILIN3, were found in the HP–depression enrichment pathway." (PMID 40918512, 2025).
metastatic disease (1 paper, 2024). "In conclusion, the presented work identified the seven genes EMILIN3, MTA1, SV2B, TMPRSS6, ACVR1C, NFAT5 and SMC3 associated with the formation of colorectal BM during the course of disease but not with liver metastasis or non-metastatic disease." (PMID 38558282, 2024).
neurofibroma (1 paper, 2024). An intraneural or extraneural neoplasm arising from nerve tissues and neural sheaths. "Upon BM remodeling, as observed in a neurofibroma skin biopsy, we found EMILIN-3 localization with anchoring fibrils." (PMID 39639116, 2024). "Localization of EMILIN-3 and collagen VII anchoring fibrils was observed by immunogold labeling in a neurofibroma skin biopsy, which could be not observed in normal skin." (PMID 39639116, 2024).
rotator cuff tears (1 paper, 2022). "Based on the risk of being damaging and on the potential role in rotator cuff etiopathogenesis, three candidate genes for rotator cuff tears were prioritized: COL23A1, EMILIN3 and HDAC10." (PMID 36358266, 2022).
tumor (5 papers, 2014 to 2025). "Previous research demonstrated the role of EMILIN/Multimerins in regulating tumor growth progression including the association of EMILIN3 in LGG survival rates." (PMID 32175193, 2020). "Although less research has been done on elastin Microfibril Interfacer 3 (EMILIN3) and cartilage acidic protein 1 (CRTAC1) in tumor immunity, previous findings suggest that CRTAC1 may influence the onset and progression of tumors by binding to calcium ions and innate immune pathways." (PMID 37405952, 2023).
cancer (2 papers, 2022 to 2024). A tumor composed of atypical neoplastic, often pleomorphic cells that invade other tissues. "MRPL38, EMILIN3 and RALYL are overexpressed in non-resistant cancer cell lines." (PMID 38443409, 2024). "It is possible that EMILIN3 and MRPL38 are not directly involved in the development of drug resistance in cancer; the fact that we were unable to find any information in the literature linking them to drug resistance reinforces this hypothesis." (PMID 38443409, 2024).
EMILIN3 also shares sentences with these, for which no sentence is quoted: Alzheimer disease (1 paper); brain tumor (1); cardiovascular disease (1); colorectal cancer (1); diabetes mellitus (1).